INS (insulin)
Diseases named in the same sentence as INS in open-access papers (continued):
Sharing a sentence is not in itself a finding about the gene and the disease.
diabetes (continued). "Patients preferred Omnipod as an insulin management system and especially the patch delivery system but preferred the A7+TouchCare personal diabetes manager to control the system." (PMID 37616289, 2023). "China’s technical guidelines for diabetes drug injection state that patients with long-term insulin injections should be screened for skin complications at least once a year." (PMID 37174907, 2023). "Although good treatment outcomes have been obtained after injecting insulin as the primary treatment for diabetes, patient adherence is still largely limited due to the fear of factors such as injection." (PMID 37514488, 2023). "The G6Pase inhibitory activity of the plant was concentrated in EAc fraction (56.8% reduction, IC50 = 14.1 μg/mL), being close to that of insulin, a drug used for diabetes (61% reduction, 100 nM)." (PMID 36903291, 2023). "Diabetes is a metabolic disease characterized by hyperglycemia due to insufficient insulin secretion, insulin inaction, or both." (PMID 36585794, 2023). "According to the obtained results, STZ-induced diabetes led to increased serum concentrations of FBG along with reduced insulin levels." (PMID 36841820, 2023). "The 100-year anniversary of the discovery of insulin is a timely reminder that altruism is central to the ethos of diabetes management." (PMID 38033993, 2023). "Recent DSSs have shown in-silico and possibly real world reduction in hypoglycaemia through modification of insulin dosing for people living with diabetes." (PMID 36755920, 2023). "This study investigated the effect of a combination of glucagon-like peptide-1 receptor agonist (GLP-1 RA) and basal insulin (BI) in poorly controlled type 2 diabetes mellitus previously treated with premixed insulin." (PMID 36897731, 2023). "In England, 40% of inpatient hospital drug charts for insulin-treated diabetes contain at least one prescription error related to insulin." (PMID 37719599, 2023). "Regarding the patients treated with insulin, 6 patients started insulin at diabetes onset, 2 patients started insulin 5 years after diabetes diagnosis and one patient 25 years after." (PMID 36793123, 2023). "GABA also has potential as a therapeutic against diabetes and has shown an inducing effect on the secretion of insulin, and it can even reverse established diabetes in a diabetic mouse model." (PMID 38004148, 2023). "Type 1 diabetes mellitus (T1D) results from the autoimmune-mediated destruction of the insulin-producing beta cells in the islets of Langerhans in the pancreas." (PMID 37458461, 2023). "In patients with diabetes, the presence of insulin resistance disrupts the delicate equilibrium between muscle protein synthesis and degradation, ultimately leading to a decline in muscle mass." (PMID 37576879, 2023). "Increasing patients' knowledge about their drugs, insulin administration, and diabetes complications improves self-care behaviors and medical adherence." (PMID 38098964, 2023). "In rats with type 2 diabetes mellitus, Bbr decreased fasting blood glucose and serum insulin levels and increased insulin sensitivity." (PMID 37298967, 2023). "Adipocyte malfunction and decreased metabolism are closely related to insulin resistance and diabetes, even though their role in insulin sensitivity/resistance is complex and poorly understood." (PMID 37047011, 2023). "CFRD is a distinct form of diabetes and is characterized by a decrease in glucose-regulated insulin secretion, whereas insulin sensitivity is most often normal." (PMID 37767091, 2023). "Elevated proinsulin relative to insulin in individuals with pre-diabetes and T2D may be caused by increased demand on beta cells to release insulin, thereby encouraging the premature release of granules that contain a higher ratio of proinsulin to mature insulin." (PMID 36693378, 2023).
diabetes (continued). "The mechanism of glucocorticoid-induced diabetes involves increasing insulin resistance, thereby affecting the glucose metabolism process, which is similar to the mechanism of type 2 diabetes." (PMID 36713831, 2023). "Parameter values for the undisturbed glucose-insulin regulatory model and obesity-related diabetes model." (PMID 36848379, 2023). "Leucine-mediated stimulation of the mammalian target of rapamycin complex 1 (mTORC1), leading to early decoupling of insulin signalling and the onset of insulin resistance, is thought to be the link between elevated BCAAs and diabetes." (PMID 37375723, 2023). "It is plausible that diabetes apps with functional modularity containing carbohydrate counting or insulin dosage are more effective." (PMID 37064701, 2023). "For a long time, it was observed that diabetes remission was affected by the time of diabetes duration, poor preoperative glycemic control, and preoperative insulin dosage." (PMID 36875493, 2023). "When T1DM and CD coexist, glucose metabolism is compromised, effective insulin therapy is hampered, and diabetes management is worsened." (PMID 38022113, 2023). "This experimental study demonstrated that STZ-induced diabetes led to a significant decrease in blood insulin levels and a notable increase in serum glucose levels." (PMID 38020229, 2023). "Ten participants managed their diabetes with diet, 10 with exercise, 44 with oral medications, and 19 with insulin." (PMID 36782282, 2023). "In previous studies, we showed that the hepatic polar protein AF6 directly regulates blood glucose homeostasis and insulin sensitivity in two murine diabetes models, specifically HFD and db/db mice." (PMID 37828052, 2023). "The comparator, MDI or IPT with a conventional tubed insulin pump, represents the two alternatives in insulin delivery in ambulatory diabetes care to a patch pump." (PMID 37814352, 2023). "Type 1 diabetes mellitus (T1DM) is an autoimmune disease secondary to the destruction of the insulin-producing β cells of the islets of the pancreas." (PMID 38187075, 2023). "From 2018 to 2030, the world insulin requirements are expected to increase parallel to the incidence of diabetes by more than 20%." (PMID 36882852, 2023). "Mutated tRNA is often associated with various diseases as it can disrupt mitochondrial function and affect insulin secretion such as type 2 diabetes mellitus (T2DM), which can lead to many syndromes." (PMID 37372155, 2023). "Diabetes is characterised by elevated blood glucose levels (hyperglycaemia) due to insufficient insulin production or the presence of insulin resistance (IR)." (PMID 37627482, 2023). "One of the major defects in type 2 diabetes mellitus is altered glucose transport, associated with defective GLUT4 translocation and impairment in the insulin signaling cascade." (PMID 36677541, 2023). "Diabetes is a long-term condition that arises when the pancreas fails to generate sufficient insulin or when the body is unable to properly utilize the insulin it generates." (PMID 37927470, 2023). "These predictors included gender, taking insulin now, weak failing kidneys, duration of diabetes, UACR, blood urea nitrogen, and serum phosphorus." (PMID 37008912, 2023). "Insulin-treated individuals were more likely to be engaged with a public diabetes service and attend public podiatry services (22.1% vs. 7.5%, p = 0.001; 17.2 vs. 3.4%, p < 0.001, respectively)." (PMID 37152098, 2023). "Analysis of the effect of glutamate on diabetes onset in vitro showed that glutamate induces insulin resistance by increasing glucose‐related protein 78 (GRP78) and phosphoenolpyruvate carboxykinase (PEPCK) expression in SK‐Hep‐1 human liver cells." (PMID 37314019, 2023). "Metformin, an oral antihyperglycemic agent that improves insulin sensitivity and fibrosis in diabetes, was used as a positive control." (PMID 37589053, 2023).
diabetes (continued). "Themes of top general app design features unsupportive of the Self-Determination Theory reported by adult with type 1 or 2 diabetes requiring insulin therapy." (PMID 36826987, 2023). "Insulin pump use, along with age, duration of diabetes, and hemoglobin A1c were all clinical predictors of TIR in school." (PMID 37929231, 2023). "In type 1 diabetes mellitus (T1DM), the deficiency most commonly occurs due to an auto-immunological destruction of pancreatic insulin-producing β cells." (PMID 36715774, 2023). "While UK participants explained diabetes as ‘balancing insulin level’, US participants explained diabetes in terms of the body’s inability to produce enough insulin or lack of it in the body’." (PMID 36791113, 2023). "Type 2 diabetes mellitus results from the combination of two factors: defective insulin secretion by pancreatic β-cells and insulin resistance of peripheral target tissues." (PMID 37671161, 2023). "We evaluated the effect of a dipeptidyl peptidase‐4 inhibitor (DPP‐4i) on the progression of obstructive coronary artery disease (OCAD) in patients with type 2 diabetes mellitus (T2DM) receiving insulin therapy." (PMID 37528628, 2023). "They found that diabetic factors such as IL-1β and insulin suppressed TFEB and suggest TFEB as a means of treating inflammation associated with diabetes, particularly aortic inflammation." (PMID 37483613, 2023). "The current findings demonstrated that diabetes control rats showed significantly decreased body weights (198 ± 10 vs. 214 ± 13 g) and insulin levels (0.28 ± 0.04 vs. 1.15 ± 0.05 ng/mL) in comparison to normal control." (PMID 36677055, 2023). "Children with diabetes differ from adults in several aspects, including their insulin sensitivity during sexual maturation, their ability to practice self-management, the variability of their eating behaviors, and their physical activity." (PMID 37232708, 2023). "We divided diabetes drugs into insulins, non-insulin generic medications, and brand name medications." (PMID 38060500, 2023). "Intraperitoneally streptozotocin induction can damage β-cells of pancreatic, and reduces insulin secretion and biosynthesis, resulting diabetes in rats." (PMID 37065797, 2023). "For example, for blood glucose level control, subcutaneous insulin injections are given in diabetes, an inconvenient and painful therapy with low patient compliance." (PMID 37367780, 2023). "A total of 349 (56.9%) participants correctly identified diabetes as a condition of high blood glucose (i.e., “sugar”), while 280 (45.7%) acknowledged it as a condition of insufficient insulin in the blood." (PMID 37772210, 2023). "This form of diabetes cannot be prevented, and insulin is necessary for patients with type 1 diabetes to survive." (PMID 38033448, 2023). "Leonard Thompson, a 14-year-old patient with severe diabetes at the Toronto General Hospital, was the first human to be treated with insulin injections; however, the clinical trial failed." (PMID 37965322, 2023). "Diabetes mellitus (DM) is a chronic metabolic disorder characterized by increased blood glucose levels as a result of insufficient insulin function and is closely related to high mortality rates." (PMID 37990213, 2023). "Hyperglycemia due to insulin shortage or insulin resistance is characteristic of diabetes, and is often known as diabetes mellitus." (PMID 37679841, 2023). "Type 2 diabetes (T2D), which constitutes the majority of total diabetes cases, develops when beta cells fail to secrete sufficient insulin to cope with increased insulin demand." (PMID 37933577, 2023). "Insulin also crosses the blood–brain barrier, regulating key central nervous system functions in persons with diabetes." (PMID 38255175, 2023). "The introduction of insulin and anti-diabetic medications reduces the microvascular complications of diabetes in clinical trials but also raises the concern of hypoglycemia." (PMID 37892937, 2023).
diabetes (continued). "Insulin-dependent diabetes mellitus was found in 5 of the 110 participants (4.6%) whose insulin secretion capacity was measured." (PMID 36755909, 2023). "A total of 14 men and 26 women participants with insulin‐treated diabetes (34 designated type 1 and 6 type 2) and labile glycaemic control were evaluated." (PMID 37562398, 2023). "Despite having been proposed as natural antioxidants, SMs have been implicated in inflammatory and immune responses, vascular homeostasis, insulin signaling, and diabetes." (PMID 37237999, 2023). "In the present study, the adequate management of diabetes by comprehensive lifestyle modification, oral antidiabetics and insulin, was a protector of carotid atherosclerosis." (PMID 37817456, 2023). "Diabetes requiring insulin therapy occurred at an average age of 10 years in 3/5 cases, while 2/5 showed pancreatic hypoplasia with impaired pancreatic exocrine function." (PMID 36672242, 2023). "Patients operated on in GFH with diabetes had a significantly increased risk of requiring more than one oral hypoglycaemic agent (OR = 2.55 (CI95% 1.45–4.48), P = 0.001) and insulin (OR = 3.24 (CI95% 1.85–5.66), P < 0.001) compared to PFH." (PMID 36795288, 2023). "The terms ‘vitamins’, ‘diabetes’, ‘insulin sensitivity’, ‘immunity’, ‘antioxidants’, and ‘type 2 diabetes’ were searched for in a database like ‘PubMed’." (PMID 37123774, 2023). "We identified 33 shared targets for breast cancer, diabetes, and PPIs including lansoprazole, omeprazole, and pantoprazole, which play a critical role in fatty acid transport, insulin resistance, apoptosis, and cancer-related signaling pathways." (PMID 37165049, 2023). "LPC is independently associated with diabetes, and hepatic arylsulfatase A increased LPC and LPA in lipid rafts, which improved muscle insulin sensitivity." (PMID 37669305, 2023). "Pregnancies (number,), glucose (value,), blood pressure (mm Hg,), skin thickness (mm,), insulin (mu U/mL,), BMI (kg/m2, [0–67.1]), diabetes pedigree function (PDF) (value, [0.078–2.42]), age (years,), and outcome (Boolean- 0, 1)." (PMID 36832284, 2023). "Dysregulation of skeletal muscle metabolism in diabetes affects insulin sensitivity and glucose homeostasis." (PMID 37699892, 2023). "Studies have shown that insulin degludec is more efficient than insulin glargine U100 at lowering the incidence of severe hypoglycemia in patients with both forms of diabetes." (PMID 38022365, 2023). "Diabetes development is characterized by the ineffectiveness of insulin, modifications in pancreatic β-cells, and higher levels of inflammation." (PMID 37764713, 2023). "Insulin plays a crucial role in fatty acid metabolism, and factors such as diabetes, low insulin levels, and insulin resistance can influence lipid compositions." (PMID 37809225, 2023). "We next conducted multivariate stepwise regression analysis to determine the independent factors affecting pancreatic β-cell function or insulin sensitivity in patients with newly diagnosed diabetes." (PMID 37077360, 2023). "The present study estimated the prevalence of DEBs and insulin restriction in a sample of Saudi adolescents and young adults with T1D using the diabetes-specific DEPS-R scale." (PMID 36837546, 2023). "The excess of thyroid hormones contributes to the occurrence of diabetes both by affecting insulin secretion and by increasing insulin resistance at the peripheral level." (PMID 37628857, 2023). "Type 2 diabetes mellitus (T2DM) is a metabolic syndrome characterized by decreased insulin sensitivity and insufficient insulin secretion, which is related to the unhealthy metabolism of sugar, fat, amino acids, water, and electrolytes." (PMID 36673456, 2023). "SCFAs are important gut microbiota metabolites that maintain intestinal physiological functions; they have beneficial effects on insulin sensitivity and a role in the mitigation of metabolic diseases such as obesity and diabetes." (PMID 37048203, 2023).
diabetes (continued). "Diabetes mellitus (DM) is a chronic disease characterised by a progressive decrease in the production of insulin or progressive tissue resistance to insulin." (PMID 37892985, 2023). "Rich in high-fiber, nutrient-dense foods, the diet supports glycemic control, insulin sensitivity, and weight management, which are all essential factors in diabetes care." (PMID 37892537, 2023). "Among patients with diabetes, there is a higher prevalence of DD in those taking insulin compared to those taking metformin (RR: 0.801, 95% CI: [0.774, 0.83])." (PMID 37443309, 2023). "It was helpful to explore the pathogenesis of diabetes from the perspective of insulin signaling pathway." (PMID 36749274, 2023). "Adult zebrafish that were overfed a commercially available fish food can exhibit symptoms of diabetes such as decreased glucose tolerance and reduced insulin expression." (PMID 37569372, 2023). "The development of severe, burning pain upon initiation of insulin therapy against diabetes was first reported in 1933." (PMID 37069517, 2023). "In our cohort, about 85% of patients took at least one medication for diabetes at hospital admission, mainly insulin or metformin." (PMID 36767972, 2023). "Our results are in accordance with the literature, which has already reported that evening chronotype subjects had a worse control of type 2 diabetes mellitus in terms of HbA1c values and the need of insulin treatment." (PMID 36986157, 2023). "As one of the 2 major drugs in the treatment of diabetes (insulin and oral hypoglycemic drugs), insulin has been a great boon for hundreds of millions of diabetic patients who need insulin treatment." (PMID 38206709, 2023). "Exercise, often referred to as “medicine”, is another intervention that assists in regulating blood glucose and insulin levels in people with diabetes, is cost-effective, and promotes a “patient-centered” lifestyle approach to metabolic health." (PMID 37606407, 2023). "We aimed to assess long-term glycemic and clinical outcomes after the use of continuous subcutaneous insulin infusion and continuous glucose monitoring in people with diabetes." (PMID 37610810, 2023). "Insulin therapy in diabetes is a major cornerstone on its treatment, but the need for multiple daily subcutaneous applications and the risk of hypoglycemia becomes a challenge regarding patient adherence." (PMID 37249450, 2023). "This accumulation of visceral fat can lead to insulin resistance and reduce the action of insulin effect, leading to failed glucose utilization in the body and a gradual increase the plasma glucose level, which leads to diabetes." (PMID 37746665, 2023). "Type 1 diabetes mellitus (T1DM) is a chronic condition arising from a failure of pancreatic β-cells to produce adequate insulin, often as a consequence of pancreatic β-cell destruction, thereby dysregulating circulating glucose level homeostasis." (PMID 36834709, 2023). "Exercise can potentially induce hypoglycemia in patients with diabetes, particularly those with T1D treated with insulin." (PMID 37830705, 2023). "Diabetes is a chronic disease that affects the ability of the body to produce or utilize insulin, which is necessary for regulating blood sugar levels." (PMID 38137029, 2023). "New treatment modalities such as flash glucose monitoring, continuous glucose monitoring, and advances in (closed-loop) continuous subcutaneous insulin infusion have shown promising results in patient outcomes and diabetes burden." (PMID 37029362, 2023). "MT was found to significantly modulate the raised blood glucose, HbA1c, and insulin levels induced by diabetes, as well as the decreased alanine aminotransferase (ALT) and aspartate aminotransferase (AST)." (PMID 37655263, 2023). "The motivation is on insulin delivery systems because of the known covalent reversible chemistry of the aryl boronic acid-based materials for the targeted treatment of diabetes mellitus." (PMID 36769081, 2023).